SCARNA7 (small Cajal body-specific RNA 7)
Synonyms: U90
Gene: Small Cajal body-specific RNA gene on chromosome 3 (160,514,907 to 160,515,236, reverse strand). Ensembl gene ENSG00000238741.
Gene Ontology:
Biological process: RNA processing
Cellular component: nucleolus
Homologues: Orthologues: chimpanzee SCARNA7 (99% identical), rabbit SCARNA7 (92% identical), dog SCARNA7 (90% identical).
Diseases named in the same sentence as SCARNA7 in open-access papers:
SCARNA7 is named in the same sentence as 3 diseases in open-access papers, as found by Europe PMC text mining. Sharing a sentence is not in itself a finding about the gene and the disease. The quoted sentences say what the papers report.
Pleural effusion (1 paper, 2020). The presence of an excessive amount of fluid in the pleural cavity. "We observed the same trend as we did in the pleural effusions, namely, significant upregulation of SCARNA7, MALAT1, and NONHSAT017369 in the EGFR‐mutant group compared to the EGFR wild‐type group (P < 0.05)." (PMID 31691525, 2020).
SCARNA7 also shares sentences with these, for which no sentence is quoted: infection (2 papers); lymph node metastasis (1).